Y_RNA (Y RNA )
Gene: Miscellaneous RNA gene on chromosome 20 (5,113,993 to 5,114,083, reverse strand). Ensembl gene ENSG00000252367.
Homologues: Orthologues: chimpanzee Y_RNA (97% identical). Paralogues in human: RNY4 (84% identical), Y_RNA (84% identical), Y_RNA (82% identical), RNY4P14 (81% identical), RNY4P6 (81% identical), Y_RNA (81% identical), RNY4P10 (80% identical), RNY4P37 (80% identical), RNY4P7 (80% identical), Y_RNA (80% identical), RNY4P13 (79% identical), RNY4P19 (79% identical), and 88 more.